PBRM1 (polybromo 1)
Diseases named in the same sentence as PBRM1 in open-access papers (continued):
Sharing a sentence is not in itself a finding about the gene and the disease.
tumor (continued). "Contrariwise, attenuated progressive diseases (longer time of metastasis, single metastatic dissemination) preferentially harboured “PBRM1 → SETD2” or “PBRM1 → PI3K” evolutionary trajectories, high ITH and low genomic instability in primary tumours." (PMID 35326534, 2022). "We showed that by calculating the median transcription values of the four ccRCC tumour suppressors of 3p25 and 3p21 chromosomal loci—VHL, SETD2, PBRM1, and BAP1–, complemented that of the p14ARF, normal and ccRCC tissues can be distinguished." (PMID 35586183, 2022). "An important role of PBRM1 in immune modulation is the suppression of IFN-γ-responsive gene expression, thus conferring T-cell-mediated killing resistance to tumor cells." (PMID 33419967, 2021). "For instance, multiple PBRM1-driven and VHL monodriver subtypes predominately progress to a solitary metastatic site, whereas ccRCC tumours with multiple clonal drivers, BAP1-driven, and VHL wildtype subtypes show rapid progression to multiple sites." (PMID 34944839, 2021). "However, we could replicate the association of PBRM1 mutation and a non-immunogenic tumor phenotype, which has been caused to be related to the downregulation of IFNγ target genes." (PMID 34215851, 2021). "As is known, the short arm of chromosome 3 is the most important region contributing to the pathogenesis of RCC, for the reason that several tumor suppressor genes, like VHL, SETD2, and PBRM1, are identified within this region." (PMID 34218253, 2021). "Primary ccRCC tumours are characterized by genomic aberrations in the tumour suppressor gene VHL as well as variations in other driver genes such as BAP1, PBRM1, and SETD2." (PMID 34944839, 2021). "PBAF, a chromatin regulatory complex (PBRM1, ARID2 and BRD7), regulates chromatin accessibility for the IFN γ pathway within tumor cells, resulting in an increased resistance to T cell–mediated cytotoxicity." (PMID 32708698, 2020). "We described that the PBRM1 transcriptional and protein levels are higher in patients with PCa, when compared to those with BPH, and correlate with tumor aggressiveness." (PMID 31212728, 2019). "GFP, wild‐type PBRM1, PBRM1–3m, and tumor‐derived mutants PBRM1‐BD2IFD and PBRM1‐T232P were transiently expressed in the cells." (PMID 30585695, 2019). "For instance, the tumor suppressor genes WT1 and PI3KR1 were hypermethylated and underexpressed in high E-score tumors whereas RUNX1 and PBRM1 were hypermethylated and underexpressed in high S-score tumors." (PMID 30902996, 2019). "In many cases the protein expression levels of PBRM1, SETD2 or BAP1 correlated with that of STAT2 or IRF9 on the same tumor samples." (PMID 30355451, 2018). "Thus, the goal of this study was to determine if PBRM1/BAF180 is important for HIF1- and HIF2-mediated transcriptional response, and if the BAF180 gene mutation is associated with HIF1A retention in H1H2 ccRCC, a tumor-suppressive factor in established ccRCC tumors." (PMID 28092369, 2017). "For instance, in tumor 5 from our stage I group, losses of ARID1A and BRM were each detected in the first three foci, whereas losses of PBRM1 and BRG1 occurred only in the third focus (left)." (PMID 27764136, 2016). "A similar result was observed when ARID1A was suppressed, suggesting that PBRM1 and ARID1A are two potent tumor suppressors that inhibit the rate of tumor growth." (PMID 27764136, 2016). "In tumor BC_2R, focal SCNAs were present in regions covering VHL, SEDT2, PBRM1 and BAP1, while focal SCNAs were only detected in the region covering VHL in the left tumor (BC_2L)." (PMID 27383411, 2016). "PBRM1 silencing results also in increased colony formation in soft agar and increases cell migration in 786-O, SN12C and TK10 cells, suggesting a tumor suppressive role for PBRM1 in ccRCC." (PMID 28326264, 2015).
tumor (continued). "In this minireview, we aim to shed light on the roles of PBRM1, SETD2, and BAP1 in the tumor metabolic and immune microenvironments, and discuss how these functions could benefit the management of advanced ccRCC." (PMID 41602827, 2026). "Furthermore, we identified CDC20 as the upstream regulator of PBRM1, which provides a novel viewpoint for CDC20 to influence tumor immunity." (PMID 39656940, 2025). "The JX-594-induced decrease in tumor volume was the most significant in tumors associated with BAP1 mutations as opposed to tumors with VHL, PBRM1, and SETD2 mutations (P < 0.01)." (PMID 40856833, 2025). "GNE-235 is a promising new PBRM1-selective inhibitor that has not yet been tested for its anti-tumor effects." (PMID 38390898, 2024). "There are other commonly lost tumor suppressors on this chromosome (VHL, SETD2 and PBRM1)." (PMID 39554490, 2024). "However, chromosome 3 is home to multiple tumor suppressors important in many cancers (VHL, SETD2, PBRM1) in addition to BAP1, making it unclear in which cancers BAP1 loss is biologically important." (PMID 39554490, 2024). "We found the genetic alterations in PBRM1 and ARID1A to be present in 15–16% of tumor cells." (PMID 37400502, 2023). "Since the hypothesis that methylation of gene promoter may affect tumor prognosis has been confirmed by several literature, we investigated whether the methylation level of WDR72 and PBRM1 genes in promoter affects the prognosis of ccRCC by MethSurv." (PMID 38048211, 2023). "IHC and ISH experiments conducted using mice subcutaneous tumor tissue sections showed that FOXP1 and PBRM1 expression was significantly lower and that for PD-L1 was significantly higher in the BART11+BART17-3p and BART11+BART17-3p+ T cells group than those in the NC and NC+ T cells groups." (PMID 35165282, 2022). "Renca is a broadly used murine RCC cell line, derived from a spontaneously arising tumor in a BALB/c background, and without known Vhl and Pbrm1 mutations." (PMID 32358509, 2020). "As shown here, clinical data suggest that negative expression of PBRM1 is correlated with advanced tumor stage, low differentiation grade, and worse patient outcome." (PMID 32582758, 2020). "A prospective study examining frozen tissue qRT-PCR of AQP1, DDX11, BAIAP2L1, and six previously identified genes (PBRM1, BAP1, SETD2, KDM5C, FOXC2, and CLIP4) showed that expression of DDX11 was a significant factor for predicting tumor aggressiveness based on Fuhrman grade." (PMID 31963294, 2020). "In PBRM1‐proficient 786‐O cells, deletion or suppression of PBRM1 did not alter cell growth in culture, but it significantly enhanced tumor growth in vivo." (PMID 30585695, 2019). "Overexpression of the tumor‐derived BD2IFD mutant or the 3m mutant failed to significantly suppress tumor growth compared to wild‐type PBRM1." (PMID 30585695, 2019). "Since it is well known that PBRM1 allows the transcription of several genes that are involved in the inhibition of cell cycle, its nuclear localization in RWPE-1 cells suggests that, in non-tumor conditions, PBRM1 exerts a tumor suppressor function." (PMID 31212728, 2019). "Although PBRM1 protein was restricted to the nuclei, in tumor cell lines in non-neoplastic cells, it was also present in vesicular-like structures that were dispersed within the cytoplasm." (PMID 31212728, 2019).
tumor (continued). "A retrospective, validated analysis found that tumours with BAP1 mutations conferred a worse prognosis, higher grade, and worse overall survival when compared to those with PBRM1 mutations or when compared to those without BAP1 mutations." (PMID 30099580, 2018). "Clinical data indicated that negative expression of PBRM1 is correlated with advanced tumor stage, low differentiation grade, and worse patient outcome." (PMID 28846693, 2017). "To investigate this possibility, we next tested whether co-losses of PBRM1 and ARID1A affect tumor growth in a xenograft model when compared to single losses." (PMID 27764136, 2016). "Finally, in order to learn the impact of combined losses, we compared the tumor growth after cells acquired losses of ARID1A, PBRM1, or both in a xenograft model." (PMID 27764136, 2016). "The tumor with the most mutated genetic landscape contained a shared SETD2 mutation and four nonshared mutations (in genes KDM5C, BAP1, and PBRM1)." (PMID 25124064, 2014). "However, when assessing how these results impact the response to anti-PD-1 treatments, administering a PD-1 antibody did not affect tumor growth or the survival of mice injected with Pbrm1-knockout Renca cells." (PMID 41602827, 2026). "Furthermore, to investigate the relationship between PBRM1 and CDC20 in RCC patients, we collected 91 tumor tissues from patients in our hospital, and immunohistochemistry was performed to detect the expression of PBRM1 and CDC20 by using IHC score calculations." (PMID 39656940, 2025). "Despite no changes in tumor growth in the SCLC-A xenografts, western blot and IHC analysis of tumors confirmed on-target drug activity of AU-24118 as indicated by efficient loss of SMARCA4, SMARCA2, and PBRM1." (PMID 38328238, 2024). "In both tumor and liquid biopsies, we identified an increased frequency of alterations in genes involved in genome integrity or chromatin remodeling, including ARID1A (15%), PBRM1 (9%), and BAP1 (14%), which were validated using an in-house-developed immunohistochemistry panel." (PMID 38191492, 2024). "PBRM1 protein is a subunit of the PBAF chromatin remodeling ATP-dependent complex necessary for ligand-dependent transcriptional activation by nuclear hormone receptors; it can act either as a tumor suppressor, for example in ccRCC, or oncogene, for example in prostate cancer." (PMID 37370768, 2023). "Secondly, we showed a tumor response of tazemetostat in only one model harboring a PBRM1 variant (out of four models harboring mutations affecting SWI/SNF complexes), considering the slow-growth of the tumor in those PDX models, and we did not test the drug in non-PBRM1-mutated models." (PMID 35326637, 2022). "However, there is little evidence regarding PBRM1 expression of the tumor vasculature, which plays an important role in the tumor microenvironment." (PMID 35205810, 2022). "Therefore, the effects of abnormal SWI/SNF subunits (including the PBRM1 gene) and MSI on tumor immune activity may be both synergistic and independent, and the former may be another important factor leading to increased tumor immunity in addition to MSI-H." (PMID 35928964, 2022). "The effects of PBRM1 expression levels in the tumor microenvironment are not well studied." (PMID 34447697, 2021). "Molecular alterations in RCC tumors have been extensively studied in the last decade, especially in ccRCC but neither identified mutations (e.g.,: VHL, BAP1, PBRM1, SETD2, KDM5C, MTOR) nor transcriptome-based ccRCC tumor sub-classification have straightforward clinical relevance." (PMID 33535553, 2021). "Tumor growth was fastest in mice with PBRM1 Low that did not receive PD-1 treatment." (PMID 34447697, 2021). "PD-1 blockade significantly reduced tumor growth of control knockout tumors and prolonged survival of mice bearing control knockout tumors, but did not exert significant changes in mice harboring Pbrm1 knockout tumors." (PMID 32358509, 2020).
tumor (continued). "Moreover, tumor tissues from PBRM1-negative ccRCC patients showed significantly higher mast cell infiltration compared to those from PBRM1-positive ccRCC patients." (PMID 33177244, 2020). "Finally, overexpression of PBRM1 variants containing point mutations in BDs 2, 4, and 5 or BD2 alone failed to suppress tumor growth in a xenograft model." (PMID 30585695, 2019). "Since ISGF3 is activated by HIF and suppressed after the loss of PBRM1, KDM5C, SETD2 or BAP1, it may function as the executioner of a negative feedback loop that potently opposes tumor growth." (PMID 30355451, 2018). "Since the suppression of PBRM1, KDM5C, SETD2 or BAP1 all lead to the reduction of ISGF3, a potent tumor suppressor, it is possible that any effective therapeutic intervention that restores ISGF3 function could benefit ccRCC patients with a wide variety of mutations." (PMID 30355451, 2018). "For VHL wild-type tumors, other therapy modalities aiming at pVHL non-related pathways controlled by tumor suppressors such as PBRM1, SETD2 or BAP1 may be more appropriate than the common anti-angiogenic treatment." (PMID 27530247, 2016). "Finally, we demonstrate in xenografts of ccRCC how losses of PBRM1 and ARID1A impact tumor growth." (PMID 27764136, 2016). "Furthermore, we dissected the contribution of PBRM1 deletion in CRC by regulating inflammatory factors, such as CCL5 and CXCL10 chemotaxis, and activating cytotoxic T cells and killer NK cells, which express NKG2D in the tumor microenvironment through activation of the NF-κB signaling pathway." (PMID 40093909, 2025). "However, the role and mechanism of PBRM1 in tumor immunotherapy have not been clarified." (PMID 38048211, 2023). "However, overexpression of PBRM1 failed to suppress tumour growth in a mouse xenograft model." (PMID 33941852, 2021). "We observed potent inhibition of tumor growth and induction of apoptosis by PRT1419 in various preclinical models of PBRM1-mutant ccRCC but not PBRM1-WT." (PMID 38371625, 2024). "We compared the tumor-cell expression profiles of BAP1-mutant tumors versus non-BAP1 and non-PBRM1-mutant tumors using snRNA-seq data and identified 563 differentially expressed genes." (PMID 36973268, 2023). "Precision medicine analysis of the tumor revealed two genomic alterations (BAP1 splice site 1729 + 1 G > A and PBRM1 N258fs*6) for which no targeted drugs or clinical trials were available." (PMID 29440675, 2018). "Despite no changesin tumor growth in the SCLC-A xenografts, immunoblotting and IHC analysis oftumors confirmed on-target drug activity of AU-24118 as indicated by efficientloss of SMARCA4, SMARCA2, and PBRM1." (PMID 39029462, 2024). "Interestingly, none of VHL, SETD2, PBRM1 and BAP1 is indicated in these marker gene lists suspecting a missing link between the well-known DNA tumour markers and the actual behaviour of tumour cells." (PMID 35586183, 2022).
cancer (187 papers, 2011 to 2026). A tumor composed of atypical neoplastic, often pleomorphic cells that invade other tissues. "Kaplan-Meier survival analysis of a previously published CRC dataset (TCGA Pan-cancer atlas, n = 594) revealed that PBRM1 deficiency was closely correlated with patients' survival rate and life expectancy." (PMID 40093909, 2025). "Supporting a central role of these genes in tumorigenesis, mice genetically engineered to express inactivated Smarca4, Arid1a, Smarcb1, or Pbrm1 alleles are prone to cancer." (PMID 41387924, 2025). "A comprehensive analysis of PBRM1 in multiple cancer types showed that the frequency of PBRM1 mutations was 8.4% in SKCM." (PMID 39530091, 2024). "We next tested the effects of cancer-associated PBRM1-BD4 missense variants on full-length PBRM1 histone Kac binding by incubating transduced Caki-2 nuclear lysates with biotin-labeled H3K14ac and H3K14/18/23/27ac peptides bound to streptavidin resin." (PMID 38460939, 2024). "Our study revealed that the PBRM1 expression level and PBRM1 mutation alone cannot fully explain the functional roles of PBRM1 in cancer." (PMID 39375538, 2024). "Several studies, from CRISPR-Cas9 screening to patient-cohort studies, have demonstrated that the loss of function in PBRM1 reduces the resistance of cancer to immune checkpoint inhibitor therapy." (PMID 39375538, 2024). "To define the cancer-associated mutational landscape affecting the PBRM1 gene, we curated the incidence of all cancer-associated PBRM1 missense mutations identified by next-generation sequencing." (PMID 38460939, 2024). "While PBRM1 loss modulates NRF2 activity in these cancers, its loss increased NRF2 activity in CESC and decreased it in ESCA, again suggesting the impact of PBRM1 loss acts in a context specific manner." (PMID 38358974, 2024). "Here, we used an array of computational, biophysical, and cellular assays to interrogate the effects of cancer-associated PBRM1 bromodomain missense variants on protein stability and function." (PMID 38460939, 2024). "This knowledge provides a foundation for drawing correlations between specific cancer-associated PBRM1 missense variants and distinct alterations in PBRM1 function, informing future cancer personalized medicine approaches." (PMID 38460939, 2024). "Since mutations in the fourth bromodomain of PBRM1 (PBRM1-BD4) comprise nearly 20% of all cancer-associated PBRM1 missense mutations, we focused our analysis on PBRM1-BD4 missense protein variants." (PMID 38460939, 2024). "LF1 levels were associated with somatic cancer driver mutations in PBRM1 and SETD2, chromatin remodelling genes linked to cell senescence and proliferation, which appears consistent with our observation that higher mitotic rates are related to these features." (PMID 39592856, 2024). "PBRM1 expression or mutation exhibits a diverse significance in predicting the prognosis of different cancers." (PMID 37175757, 2023). "The RT-qPCR results of our BAH mutants revealed multiple gene classes (with links to PBRM1-associated cancers) that became dysregulated upon BAH1 and BAH2 mutation." (PMID 37394010, 2023). "To analyze the role of the missense mutation, in-frame deletions and insertions of PBRM1, we selected a pan-cancer dataset IMPACT2018 with relatively more cases of PBRM1 missense mutation, in-frame deletions (no in-frame insertion in this dataset)." (PMID 36313281, 2022). "PBRM1 loss in both cancer and endothelial cells was associated with a lower recurrence-free survival rate (p < 0.001)." (PMID 35205810, 2022). "Survival curve analysis showed that the 5-year RFS rate was significantly lower in patients with PBRM1 loss than in those with PBRM1 retained in cancer cells (71.1% versus 96.1%, p < 0.001)." (PMID 35205810, 2022). "To investigate the association between PBRM1 mutations and immune response in multiple cancers, we conducted compressive analyses of immune-related genes for each cancer type." (PMID 36699446, 2022).